COL11A1 (collagen type XI alpha 1 chain)
Diseases named in the same sentence as COL11A1 in open-access papers (continued):
Sharing a sentence is not in itself a finding about the gene and the disease.
ovarian carcinoma (57 papers, 2010 to 2025). A malignant neoplasm originating from the surface ovarian epithelium. "In this study, we found that miR-509-3p expression was reduced in ovarian cancer, was mediated by the hypermethylation of the promoter region of the miR-509-3p gene, and significantly associated with a poor prognosis and COL11A1 expression." (PMID 37386587, 2023). "Collagen type XI alpha 1 (COL11A1) is a novel biomarker associated with poor survival in ovarian cancer and a promoter of ovarian cancer cell resistance to cisplatin." (PMID 34638339, 2021). "Our group and others have demonstrated that elevated expression of COL11A1 is associated with poor survival, recurrence, and cisplatin resistance in ovarian cancer." (PMID 34638339, 2021). "This is the first study to demonstrate miR-335 expression and its association with COL11A1 in various ovarian cancer cell lines and clinical specimens." (PMID 34944877, 2021). "Collagen type IX alpha 1 (COL11A1) has emerged as not only a biomarker associated with poor clinical outcomes in ovarian cancer, but also an important molecular player that promotes ovarian cancer cisplatin resistance." (PMID 34638339, 2021). "Recent studies have found that COL11A1 is associated with various cancers, such as gastric cancer, ovarian cancer and non‐small cell lung cancer." (PMID 33932142, 2021). "In ovarian cancer, COL11A1 is primarily expressed by cancer-associated fibroblasts (CAFs), although cisplatin-resistant ovarian cancer cells have also been shown to express COL11A1." (PMID 34638339, 2021). "Collagen type XI alpha 1 (COL11A1) is a novel biomarker associated with cisplatin resistance in ovarian cancer." (PMID 32312965, 2020). "COL11A1 was overexpressed in bowel metastases among patients with ovarian cancer, and promoted ovarian cancer progression and is associated with chemo-resistance to cisplatin and paclitaxel in ovarian cancer cells." (PMID 33542901, 2020). "In patient tumors, FAO is increased concurrently with COL11A1 and is associated with poor survival in recurrent ovarian cancer." (PMID 32312965, 2020). "In the current study, we elucidated a novel molecular mechanism underlying the therapeutic action of SC66 in ovarian cancer cells, especially COL11A1-mediated chemoresistance." (PMID 30975980, 2019). "COL11A1 overexpression has been shown to be associated with progression in several cancers, including ovarian cancer." (PMID 26087191, 2015). "In ovarian cancer, COL11A1 is associated with poor outcomes." (PMID 40927672, 2025). "While it remains unclear how COL11A1 might contribute to the poor outcomes in ovarian cancer, we observed that areas enriched for COL11A1 are associated with altered ECM texture and pattern, including fiber linearization." (PMID 36497028, 2022). "A t-SNE plot of the ovarian cancer single-cell RNA sequencing profile of the tumor microenvironment shows that COL11A1, ACTA2 (gene encoding for α-SMA), and PDPN are expressed in different, partially overlapping, ovarian CAF subsets, with COL11A1 exhibiting the most restricted expression." (PMID 36497028, 2022). "Furthermore, high levels of COL11A1 protein secretion have been linked with resistance to platinum-based therapies in ovarian cancer." (PMID 35847935, 2022). "Furthermore, high levels of COL11A1 protein secretion has been linked with resistance to platinum-based therapies in ovarian cancer." (PMID 33668097, 2021). "Curiously, in our studies, single knockdown of a either integrin α1β1 or DDR2 has been sufficient to attenuate most COL11A1 downstream signaling in ES2 ovarian cancer cells, although DDR2 knockdown caused more inhibition of COL11A1 downstream signaling than ITGα1 knockdown." (PMID 33668097, 2021). "Furthermore, we observed that depletion and drug inhibition of HSP27 makes ovarian cancer cells grown on COL11A1 to be more susceptible to cisplatin treatment." (PMID 34638339, 2021).
ovarian carcinoma (continued). "The association of miRNAs and lncRNA with COL11A1 in ovarian cancer still warrants investigation." (PMID 34944877, 2021). "COL11A1 is mainly expressed by cancer-associated fibroblasts adjacent to cancer cells in ovarian cancer, although there is also evidence that cisplatin-resistant ovarian cancer cells also express high levels of endogenous COL11A1." (PMID 34638339, 2021). "However, the mechanisms underlying how COL11A1 confers cisplatin resistance in ovarian cancer are poorly understood." (PMID 32312965, 2020). "The study revealed through gene expression profiling that COL11A1 expression escalates during ovarian cancer progression, serving as an indicator of poor clinical outcomes in patients with epithelial ovarian cancer." (PMID 39845732, 2025). "Extensive research indicates that COL11A1 expression is elevated in various cancer types, including ovarian cancer, breast cancer, oral squamous cell carcinoma, lung adenocarcinoma, and colorectal carcinoma, among others." (PMID 39845732, 2025). "For instance, co-cultivation of ovarian cancer cells with CAFs or on the plates pre-coated with COL11A1 attenuates cisplatin-induced apoptosis." (PMID 38818409, 2024). "Collagen type XI alpha 1 (COL11A1) is expressed mostly in recurrent and chemo-resistant ovarian cancers and also a subgroup of tumor-adjacent cancer associated fibroblasts (CAFs)." (PMID 38741195, 2024). "First, we examined the expression of the three DNMTs in ovarian cancer cells with different COL11A1 expression statuses." (PMID 37386587, 2023). "Our finding that COL11A1 transcript and protein expression is associated with shortened OS and DFS is consistent with findings in ovarian cancer and complementary to findings that elevated COL11A1 expression is associated with chemoresistance in human tumors." (PMID 37509222, 2023). "We have previously demonstrated that COL11A1 confers chemoresistance to ovarian cancer cells through the activation and phosphorylation of Akt and phosphoinositide-dependent kinase-1 (PDK1) stabilization." (PMID 37386587, 2023). "In ovarian cancer cells, COL11A1 modulates TGF-β3 via the NF-κB/IGFBP2 axis, thereby activating cancer-associated fibroblasts and influencing tumor development and migration." (PMID 36843929, 2023). "Previously, we demonstrated that miR-335 is crucial for preventing collagen type XI alpha 1 (COL11A1)-mediated epithelial ovarian cancer (EOC) progression and chemoresistance." (PMID 36865240, 2023). "There results indicate that COL11A1 downregulates miR-509-3p expression in ovarian cancer cells by inhibiting the binding of DNMT1 to the miR-509-3p promoter." (PMID 37386587, 2023). "In our opinion, COL11A1 and Akt play roles as predictive markers in the prognosis of cancer and as drug design targets in epithelial ovarian cancer." (PMID 35847935, 2022). "COL11A1 induced chemoresistance and exerted anti-apoptotic effects in ovarian cancer cells by mediating the transcriptional activation of NF-κB to upregulate the Twist family." (PMID 36236019, 2022). "Our present study showed that COL11A1 upregulates IGFBP2 transcription by augmenting p65 DNA-binding activity in ovarian cancer cells to constitutively activate the TGF-β3 signaling pathway, thereby promoting CAF activation." (PMID 35847935, 2022). "We demonstrated that TGF-β1 directly acts on the NF-YA binding site of the promoter of COL11A1 in ovarian cancer cells, activating COL11A1 and thereby inducing migration and invasion." (PMID 35847935, 2022). "The processes of promoting tumor formation and activating CAFs can be attuned by TGF-β3 antibodies, suggesting a promising treatment target in COL11A1-positive ovarian cancer." (PMID 35681617, 2022). "Our report showed that SC66, an Akt inhibitor, was found to inhibit the proliferation of various human ovarian cancer cells in vitro, and the sensitivity of ovarian cancer cells to SC66 was negatively correlated with the content of COL11A1 in cells." (PMID 35847935, 2022).
ovarian carcinoma (continued). "In ovarian cancer tissues, miR-335 inhibits the expression of COL11A1 and thus weakens the invasion ability of ovarian cancer." (PMID 36160004, 2022). "Solanum incanum extract (also known as SR-T100), has been shown to downregulate c/EBPβ and COL11A1 expression, thereby sensitizing melanoma and ovarian cancer cells to cisplatin." (PMID 33668097, 2021). "We performed assays to discover the biological molecules that are activated by COL11A1 in ovarian cancer cells." (PMID 34638339, 2021). "COL11A1 overexpression promotes the progression of epithelial ovarian cancer (EOC) progression and induces chemoresistance." (PMID 34944877, 2021). "Collectively, these results suggest that HSP27, whose expression and activity is upregulated by COL11A1, is a marker for poor prognosis in ovarian cancer." (PMID 34638339, 2021). "Collectively, these results suggest that HSP27 mediates COL11A1-induced cisplatin resistance in ovarian cancer cells." (PMID 34638339, 2021). "In ovarian cancer, COL11A1 is expressed in the intra/peri-tumoral stromal cells and rare foci of tumor epithelial cells, indicating COL11A1 as a marker of carcinoma-associated fibroblasts and possibly cancer cells undergoing EMT." (PMID 35095892, 2021). "Although inhibition of COL11A1-induced FAO sensitized ovarian cancer cells to cisplatin treatment in vitro, there have been no clinical trials that use FAO inhibitors for cancer treatment yet." (PMID 33668097, 2021). "COL11A1 signaling in ovarian cancer cell lines makes them more addicted to fatty acid metabolism to drive cisplatin resistance." (PMID 33668097, 2021). "We previously established that COL11A1 promotes cisplatin resistance in ovarian cancer cells through activation of NFkB and upregulation of specific inhibitors of apoptosis (IAPs; BIRC2, BIRC3, and XIAP)." (PMID 34638339, 2021). "We previously reported that FAO is upregulated by COL11A1 to confer cisplatin resistance in ovarian cancer cells." (PMID 34638339, 2021). "In line with this study, it has been shown that in the ECM of ovarian cancer, COL11A1 is aligned in thin linear collagen fibrils whereas type I collagen forms dense wavy collagen fibrils." (PMID 33668097, 2021). "Another group has also found that COL11A1 activates Akt/NFκB signaling in multiple human ovarian cancer cell lines." (PMID 33668097, 2021). "Although there have been efforts to detail out the mechanisms by which COL11A1 confers cisplatin resistance to ovarian cancer cells, there are still knowledge gaps in the COL11A1 signaling pathway." (PMID 34638339, 2021). "We next investigated if HSP27 mediates COL11A1-induced cisplatin resistance in ovarian cancer cells." (PMID 34638339, 2021). "We and others have shown that ovarian cancer cells bind to COL11A1 through the integrin heterodimer α1β1 and DDR2." (PMID 33668097, 2021). "Overall, this study identifies HSP27 as a potential target to treat cisplatin-resistant ovarian cancer patients who often overexpress COL11A1." (PMID 34638339, 2021). "We determined that DDR2/integrin α1β1 and Src/Akt signaling mediate COL11A1 induction of total and phosphorylated HSP27, and that HSP27 mediates COL11A1-induced ovarian cancer cisplatin resistance." (PMID 34638339, 2021). "We identified COL11A1 using an online prediction algorithm to search for miR-335 control targets involved in ovarian cancer proceeding, which supposedly has a miR-335 combining site in the 3′UTR." (PMID 34944877, 2021). "COL11A1 expression is upregulated in many cancers, including colorectal, breast, and ovarian cancer, and head and neck squamous cell carcinoma." (PMID 33428592, 2021). "Immunohistochemical studies in pancreatic and ovarian cancers identify a subset of CAFs marked by high COL11A1 expression." (PMID 33668097, 2021). "COL11A1 expression is upregulated in several cancer types, including ovarian cancer, breast cancer, pancreatic cancer, non-small-cell lung cancer, and colorectal cancer." (PMID 34944877, 2021).
ovarian carcinoma (continued). "We have shown that COL11A1 enhances Src/Akt/NFκB activation in human ovarian cancer cell lines, leading to upregulation of inhibitor of apoptosis protein (IAP) expression (BIRC2, BIRC3, XIAP)." (PMID 33668097, 2021). "Given COL11A1’s involvement in signaling ovarian cancer cell cisplatin resistance, we next explored the link between COL11A1 and HSP27." (PMID 34638339, 2021). "Akt inhibition has been shown to attenuate COL11A1 signaling and cisplatin resistance in ovarian cancer cells, making it an obvious COL11A1 downstream effector molecule to target." (PMID 33668097, 2021). "This study identifies HSP27 as a novel and druggable downstream molecule of COL11A1 to attenuate cisplatin resistance in ovarian cancer cells." (PMID 34638339, 2021). "Xenograft mouse models and cell lines derived from lung metastasis in renal carcinoma, breast cancer tissues, lung cancer tissues and cell lines, and drug-resistant and invasive cell lines and xenografts of ovarian cancer also show elevated COL11A1 expression." (PMID 33668097, 2021). "We have also discovered that COL11A1 confers cisplatin resistance through switching the metabolic preference of ovarian cancer cells to fatty acid metabolism." (PMID 34638339, 2021). "This study identifies the small heat shock protein 27 (HSP27) as a novel COL11A1 effector molecule that mediates COL11A1-induced cisplatin resistance in ovarian cancer cells." (PMID 34638339, 2021). "The mRNA expressions of COL11A1 were analyzed by real-time reverse transcription (RT)-PCR in either overexpressing or inhibiting miRNAs in ovarian cancer cells." (PMID 34944877, 2021). "We demonstrated that phosphorylation of AMPK (indicative of AMPK activation) was increased by COL11A1 as early as 2.5 h and was retained until 96 h in ovarian cancer cells." (PMID 32312965, 2020). "Collectively, our results demonstrate that COL11A1 increases de novo fatty acid synthesis through DDR2-Src-Akt-AMPK signaling to upregulate FAO in ovarian cancer cells." (PMID 32312965, 2020). "We identified that fatty acid β-oxidation (FAO) is upregulated by COL11A1 in ovarian cancer cells and that COL11A1-driven cisplatin resistance can be abrogated by inhibition of FAO." (PMID 32312965, 2020). "In summary, we identified that COL11A1 increases FAO in ovarian cancer cells to confer cisplatin resistance and COL11A1 and FAO are concurrently upregulated in recurrent ovarian tumors." (PMID 32312965, 2020). "Our results provide novel therapeutic strategies to treat cisplatin-resistant recurrent ovarian cancers which typically express high levels of COL11A1." (PMID 32312965, 2020). "Some study suggested that Twist promotes platinum resistance in ovarian cancer via activation of collagen type XI alpha 1 (COL11A1), GAS6, L1CAM, and Akt signaling." (PMID 33076245, 2020). "Collectively, our results suggest that COL11A1 inhibits cisplatin-induced apoptosis by upregulating FAO in ovarian cancer cells." (PMID 32312965, 2020). "Previously, we revealed that COL11A1 is an important factor in Akt regulation and chemoresistance in ovarian cancer via its activation of the Akt/COL11A1/c/EBP pathway and reduction of PDK1 degradation." (PMID 32194423, 2020). "Here, we report another mechanism by which COL11A1 confers cisplatin resistance by regulating ovarian cancer cell metabolism." (PMID 32312965, 2020). "Taken together, our results suggest that COL11A1 upregulates fatty acid metabolism in ovarian cancer cells in a DDR2-Src-Akt-AMPK dependent manner." (PMID 32312965, 2020). "Nevertheless, it is interesting that ovarian cancer cells can upregulate both synthesis and oxidation of fatty acids in the presence of COL11A1." (PMID 32312965, 2020). "COL11A1 promotes chemoresistance in ovarian cancer; COL11A1 increases the expression of TWIST1, a master EMT regulator directly involved in generating a breast CSC phenotype." (PMID 31334229, 2019).
ovarian carcinoma (continued). "COL11A1 induced chemoresistance and exerted antiapoptosis effects in ovarian cancer cells by mediating the transcriptional activation of NF-κB to upregulate the Twist family." (PMID 31521169, 2019). "We previously demonstrated that COL11A1-mediated nuclear factor-κB activation promoted the expression of TWIST1 and Mcl-1, factors associated with chemoresistance and anti-apoptosis in ovarian cancer cells." (PMID 30975980, 2019). "In ovarian cancer, COL11A1 mRNA levels correlated with disease progression and survival, and its expression is thought to mediate tumour invasiveness." (PMID 28331057, 2017). "Our data show that COL11A1 is induced by cisplatin and paclitaxel through Akt/c/EBPβ in various ovarian cancer cell lines, including A2780CP70 (endometrioid), IGROV1 (mixed), ES2 (serous), and OVCAR4 (serous)." (PMID 26087191, 2015). "We also observed that phosphorylated Akt levels in chemoresistant ovarian cancer cells were increased by COL11A1 via increased binding activity between PDK1 and COL11A1." (PMID 26087191, 2015). "The over-expression of COL11A1 reportedly correlates with lymph node metastasis and poor prognosis in non-small cell lung cancer and ovarian cancer." (PMID 26352260, 2015). "This study demonstrated that the c/EBPβ binding site in the COL11A1 promoter (−541/−203) is necessary for activation of transcription by cisplatin and paclitaxel in chemoresistant ovarian cancer cells." (PMID 26087191, 2015). "Studies have shown that COL11A1 promotes tumor cell invasion through multiple mechanisms, leading to a poor prognosis in diseases such as ovarian cancer, head and neck squamous cell carcinoma, pancreatic cancer, gastric cancer, colorectal cancer, and certain sarcomas." (PMID 39857819, 2025). "Additionally, a novel biomarker, Collagen type XI alpha 1 (COL11A1), has been found to induce platinum resistance by upregulating fatty acid metabolism in ovarian cancer through its binding to discoid domain receptor 2 and activating Src-Akt-AMPK signaling." (PMID 37681030, 2023). "Notably, COL11A1 has been shown to induce chemoresistance to cisplatin and paclitaxel in ovarian cancer cells through the AKT and Twist1 pathways." (PMID 37207166, 2023). "Another report from us has revealed that COL11A1 could increase phosphorylated Akt in chemoresistant ovarian cancer cells by stabilizing PDK1 protein." (PMID 35847935, 2022). "COL11A1 promotes the phosphorylation of SP1, which in turn promotes the transcriptional activation of IKKβ, leading to the increased expression of Twist1 induced by NF-κB, thus causing drug resistance in ovarian cancer cells." (PMID 35847935, 2022). "Akt inhibitor SC66 reverses the cisplatin resistance in ovarian cancer by inhibiting COL11A1." (PMID 36160004, 2022). "At present, several biomarkers of ovarian cancer have been found, such as COL11A1 and POSTN." (PMID 35813831, 2022). "Collectively, this study identifies HSP27 as a novel and druggable COL11A1 downstream effector molecule that may be targeted to overcome cisplatin resistance in recurrent ovarian cancer, which often overexpress COL11A1." (PMID 34638339, 2021). "Interestingly, we also discovered that fatty acid oxidation (FAO) compensates for the loss of HSP27 in ovarian cancer cells cultured on COL11A1 and dual inhibition of FAO and HSP27 is lethal to cisplatin-resistant ovarian cancer cells cultured on COL11A1." (PMID 34638339, 2021). "Similarly, in ovarian cancer specimens, the expression of COL11A1 is the highest in recurrent tumors compared to primary and metastatic tumors, suggesting that COL11A1 promotes tumor recurrence post chemotherapy." (PMID 33668097, 2021). "In summary, we demonstrated that HSP27 is a novel COL11A1 downstream effector molecule that may be inhibited to treat COL11A1-positive cisplatin-resistant ovarian cancers." (PMID 34638339, 2021). "Finally, we have discovered that COL11A1 switches the metabolic profile of ovarian cancer cells to fatty acid metabolism." (PMID 33668097, 2021).